Y_RNA (Y RNA )
Gene: Miscellaneous RNA gene on chromosome X (23,782,210 to 23,782,310, forward strand). Ensembl gene ENSG00000202272.
Homologues: Orthologues: chimpanzee Y_RNA (99% identical), macaque Y_RNA (96% identical). Paralogues in human: Y_RNA (86% identical), Y_RNA (85% identical), Y_RNA (84% identical), RNY1P1 (83% identical), RNY1P5 (83% identical), Y_RNA (83% identical), Y_RNA (82% identical), Y_RNA (81% identical), RNY1 (80% identical), RNY1P11 (80% identical), Y_RNA (80% identical), RNY1P16 (79% identical), and 93 more.